IGF1 (insulin like growth factor 1)
Diseases named in the same sentence as IGF1 in open-access papers (continued):
Sharing a sentence is not in itself a finding about the gene and the disease.
COVID-19 (continued). "This may explain the same direction from the IVW analysis of IGF-1, estradiol, and COVID-19 outcomes." (PMID 36250974, 2022). "Furthermore, recent studies show that higher IGF1 level is associated with lower incidence of T2DM and lower risk of COVID-19 mortality." (PMID 36532549, 2022). "More studies are required to determine whether novel therapeutic strategy targeting on IGF-1 pathway might improve COVID-19 prognosis." (PMID 36250974, 2022). "Sex hormones, SHBG, IGF-1, and COVID-19 outcomes in Mendelian randomization (MR) analyses." (PMID 36250974, 2022). "Associations of IGF-1 levels with COVID-19 susceptibility and hospitalization were not statistically significant after Bonferroni correction, albeit showing a nominal significance at p<0.05." (PMID 36250974, 2022). "IGF-1 and COVID-19 outcomes in Mendelian randomization (MR) analyses." (PMID 36250974, 2022). "Here, we figured out a higher level of IGF1 in early stage of infection in COVID-19 patients." (PMID 35095832, 2021). "However, the regulatory mechanisms of IGFALS and IGF-1 in COVID-19 remain elusive, and further studies are needed to determine the functional roles of both proteins in the pathogenesis of the disease." (PMID 34667241, 2021). "The significant association between the gene set containing these genes and COVID-19 hospitalization suggests there may be a genetic basis for the previously reported associations between protein levels of PDE3A and IGF-1 with severe COVID-19." (PMID 35222515, 2021). "In addition, IGF-1 and hepatocyte growth factors were also known as antifibrogenic agents that help reduce inflammation-mediated fibrosis in the lungs of COVID-19 patients." (PMID 34306612, 2021). "The role of IGF-1 has also been investigated in the setting of COVID-19." (PMID 34452353, 2021). "Hence, upregulated IGF1 signaling could be a host response toward elevated glucose in severe COVID-19." (PMID 36768847, 2023). "We could not assess the sex-specific associations in IGF-1 and COVID-19 due to no data by sex in HGI." (PMID 36250974, 2022). "To further validate the findings, as disease severity progresses in patients with COVID-19, we detected a concomitant rise in serum cytokine levels associating immune cell communication, such as IL6, IL10, IGF1, and GALECTIN-1, may play roles on reduction and exhaustion of T cell populations." (PMID 34238338, 2021). "However, there were few researches focusing on the relationship of IGF1 and COVID-19." (PMID 35095832, 2021). "This is the first study showing that the blood levels of GH, IGF-1, BDNF, and PDGF are reduced during acute severe COVID-19 and that the reduced levels persist for at least six months after recovery." (PMID 40709999, 2025). "Together, these results indicate reduced expression of IGFBP2 and its selective ligands IGF1 and IGF2 specifically in AEC2 cells from patients diagnosed with severe or moderate COVID-19." (PMID 40121473, 2025). "This study aims to assess the prognostic capacity of circulating IGF-1, HFABP, and ETP, levels for COVID-19 severity progression in Egyptian patients." (PMID 37189123, 2023). "Another recent study confirmed other previous studies that revealed that the insulin/insulin-like growth factor 1 (IGF) signaling pathway, which plays an important role in energy metabolism, is impaired in organs and tissues of severe COVID-19 patients." (PMID 36947108, 2023). "Sensitive analysis between serum IGF-1 levels instrumented by 10 SNPs in the IGF-1 gene region and COVID-19 outcomes." (PMID 36250974, 2022). "After comparing the collected genes, 460 host factors common to COVID-19 and dengue were found, including MMP2, PDF, PFKP, SLC25A3, IGF1, CCL4, TLR4, and AhR, and further analysis of interaction networks was performed." (PMID 34394108, 2021). "The upregulation of IGF-1 and IGF-1R has been observed in the lung tissues of patients with ARDS related to COVID-19." (PMID 34452353, 2021).
COVID-19 (continued). "Research has indicated the upregulation of IGF-1 and IGF-1R in the lung tissues of patients with ARDS related to COVID-19." (PMID 34452353, 2021). "In addition, IGF1 and EGF were central nodes and are both factors that influence various biological processes in COVID-19." (PMID 41227320, 2025). "Their effects in COVID-19 patients could be part of hyperinflammation for MAPK3, whereas IGF1 and EGF signaling if overactivated it can lead to fibrosis." (PMID 41227320, 2025). "Apart from IGF-1 and testosterone, no horizontal pleiotropy effect was found in either direction for any of the three COVID-19 phenotypes, which indicates the validity of the significant findings in the univariable MR analysis." (PMID 36836216, 2023). "Testosterone, estradiol, and IGF-1 concentrations were similar in women with and without severe COVID-19." (PMID 34032853, 2021). "The identified crucial cytokine panel, including IL6, IL1β, IL10, CXCL10, IGF1, and GALECTIN-1, may offer the selective targets to improve the efficacy of COVID-19 therapy." (PMID 34238338, 2021). "Irrespective of COVID-19, IGF-1 levels diminish gradually in later fibroproliferative stages, and show a negative correlation with mortality in patients with ARDS28,29." (PMID 34667241, 2021). "IGF1 and EGF support tissue repair after lung injury from SARS-CoV-2, aiding regeneration, but dysregulation of these factors may impair recovery, contributing to fibrosis, particularly in severe COVID-19 or long COVID." (PMID 41227320, 2025). "Thus, the finding of low serum IGF-1 levels and zSDS–IGF-1 in COVID-19 patients at admission should predict more severe disease and could lead to more rapid and necessary therapeutic measures, modulating FXR expression." (PMID 36851702, 2023). "However, we are aware that in view of the small sample size and the complex clinical picture of SARS-CoV-2 infection, the single IGF-1 value is not sufficient to discriminate all patients hospitalized for COVID-19." (PMID 36851702, 2023). "IGF-1 did not significantly affect the severity or mortality in COVID-19 patients." (PMID 36286038, 2022).
colitis (40 papers, 2011 to 2025). Inflammation of the colon. "In pituitary-intact rats, ghrelin stimulated the release of growth hormone from the pituitary gland and increased the serum level of IGF-1, and these effects were associated with therapeutic effects of ghrelin in acetic acid-induced colitis." (PMID 30934722, 2019). "We show that p38α signaling regulates IGF‐1 expression in intestinal macrophages and that IGF‐1 signaling promotes colitis and inflammation‐associated colon tumorigenesis." (PMID 29907597, 2018). "Our present study showed that apart from the acceleration of mucosal damage healing, other mechanisms of therapeutic effect of ghrelin in colitis are also associated with the release of endogenous growth hormone and IGF-1." (PMID 28538694, 2017). "Indeed, higher levels of IGF1 are linked to the maintenance of the epithelial intestinal cell barrier in murine colitis." (PMID 38891888, 2024). "Moreover, genetic or pharmacological inhibition of IGF‐1 suppresses inflammatory cell recruitment and reduces colitis‐associated tumor burden." (PMID 29907597, 2018). "To directly examine this, we studied bones from a mouse model of IBD using dextran sodium sulfate (DSS)-induced colitis and investigated the potential of ablating the expression of Socs2 to endogenously elevate GH and IGF-1 function, and correct the bone loss observed in murine colitis." (PMID 29343614, 2018). "Moreover, we found that those changes in growth hormone and IGF-1 level were associated with acceleration of healing of acetic acid-induced colitis." (PMID 28538694, 2017). "A recent study showed that heterozygous mice with an IGF-1 gene deletion exhibited a reduction in intestinal fibrosis in a trinitrobenzene sulfonic acid-induced colitis model." (PMID 40862456, 2025). "Xu and the team found that the infusion of human embryonic stem cells (T-MSCs) into mice reduced colitis by increasing the level of IGF-1 in the blood." (PMID 40534879, 2025). "In another study, it was observed that an increase in IGF-1 levels after the intravenous infusion of mesenchymal stem cells (MSCs) derived from human ESCs also alleviated colitis in mice by maintaining epithelial cell integrity, repair and regeneration." (PMID 36835075, 2023). "Hypophysectomy increased the severity of acetic acid-induced colitis and eliminated the effect of ghrelin on growth hormone and IGF-1 secretion, as well as abolished the healing-promoting effect of ghrelin on colitis." (PMID 30934722, 2019). "At d5, the IGF-1 concentrations in both the colitis and pair-fed groups were further decreased compared with those at d3 (t = 2.89, P = 0.012; t = 3.42, P = 0.004) and were significantly lower than those in the control group (P < 0.05)." (PMID 31221091, 2019). "The next studies were performed to examine the role of growth hormone and insulin-like growth factor-1 (IGF-1) in the therapeutic effect of ghrelin in the course of acetic acid-induced colitis." (PMID 30934722, 2019). "At d3, the IGF-1 concentrations were significantly lower in the colitis group than those in the control group and pair-fed group (P < 0.05)." (PMID 31221091, 2019). "A previous study concluded that inflammation itself has a harmful effect on linear growth, likely due, in part, to a reduction in the plasma concentrations of IGF-1 through a rat colitis model induced by trinitrobenzenesulphonic acid (TNBS)." (PMID 31221091, 2019). "This study also provides an improved understanding of the relative effects of GH/IGF-1 on bone health in experimental colitis and is consistent with data reporting the beneficial effects of GH on bone in conditions such as juvenile idiopathic arthritis." (PMID 29343614, 2018). "This study also provides an improved understanding of the relative effects of GH/IGF-1 signaling on bone health in experimental colitis, information that is essential before these drugs are explored as bone protective agents in children and adults with IBD." (PMID 29343614, 2018).
colitis (continued). "In summary, our results provide evidence that the myeloid p38α/IGF‐1 axis facilitates inflammatory cell recruitment in response to DSS‐induced colitis and contributes to CAC (Fig EV5)." (PMID 29907597, 2018). "Hypophysectomy reduced serum levels of GH and IGF-1 and increased the area of colonic damage in rats with colitis." (PMID 28538694, 2017). "Therapeutic effect of ghrelin in experimental colitis is mainly mediated by the release of endogenous growth hormone and IGF-1." (PMID 28538694, 2017). "The next form of evidence showing that the therapeutic effect of ghrelin in the course of colitis depends on the release of endogenous growth hormone and IGF-1 was obtained in hypophysectomized rats treated with ghrelin." (PMID 28538694, 2017). "This concept is additionally supported by the observation that growth hormone and IGF-1 exhibit therapeutic effects in colitis." (PMID 28538694, 2017). "The most important finding of our present study is the observation that the therapeutic effect of ghrelin in the course of colitis is related to the release of endogenous growth hormone and IGF-1." (PMID 28538694, 2017). "Our concept that the therapeutic effect of ghrelin in colitis is related to the release of endogenous growth hormone and IGF-1 is supported by our current data obtained from hypophysectomized rats." (PMID 28538694, 2017). "By analogy, we can expect the similar healing-promoting effect of IGF-1 in hypophysectomized rats with colitis." (PMID 28538694, 2017). "Reduced colitis in mice by increasing the amount of IGF-1 in the blood." (PMID 40534879, 2025). "Similarly, IGF-1 has the potential to attenuate intestinal damage and promote mucosal repair in colitis." (PMID 40221757, 2025). "It appears that IGF-1 release may be the main therapeutic mechanism in the treatment of experimental colitis with ghrelin." (PMID 39594627, 2024). "In immunocompromised mice, insulin-like growth factor 1-coated sutures and systemic insulin-like growth factor-1 administration have been shown to improve anastomotic strength and hydroxyproline content in a mouse model of colitis." (PMID 39337124, 2024). "IGF-1 signaling is involved in the regeneration of GCs in colitis." (PMID 36835075, 2023). "In addition, they stimulate colon epithelial integrity and repair by increasing the proliferation of IECs in part by enhancing circulating insulin-like growth factor-1 (IGF-1) in colitis rodents." (PMID 36707899, 2023). "An increase in the number of GCs by 76% in colonic epithelium after the IGF-1 infusion was observed in rats with DSS-induced colitis, which may suggest a direct protective action of IGF-1 on the colonic epithelium." (PMID 36835075, 2023). "This indicated IGF-1 plays an important role in the treatment, while other mechanisms may also work together to reduce colitis." (PMID 33204338, 2020). "This indicated that the IGF-1 level was increased in an early repair stage of the DSS colitis model and might play a role in mucosal regeneration." (PMID 33204338, 2020). "Thus, we found that the IGF-1 level in rats in the colitis group decreased significantly at d3 and further decreased at d5." (PMID 31221091, 2019). "The aim of the present study was to examine whether administration of ghrelin affects the course of acetic acid-induced colitis and to determine what is the role of growth hormone (GH) and insulin-like growth factor-1 (IGF-1) in this effect." (PMID 28538694, 2017). "However, experiments performed on hypophysectomized rats indicated that the anti-inflammatory effect of ghrelin in acetic acid-induced colitis is related to the release of endogenous growth hormone and IGF-1." (PMID 28538694, 2017). "In addition, recently, it was found that MSCs enriched in the liver after intravenous injection could induce the liver to secrete insulin like growth factor 1 to reduce inflammation in colitis." (PMID 38831179, 2024).
colitis (continued). "Indeed, high enrichment of acute colitis-related functional terms with pro-inflammatory cytokines and IGF1-Akt signaling pathway (upper network) agrees well with the proven regulatory role of the latter in colon inflammation and inflammation-induced mucosal injury." (PMID 36901742, 2023). "Similarly, IGF-1 promoted colonic epithelial integrity and regeneration in colitis mice." (PMID 36406080, 2022). "Research on inflammatory bowel disease, colitis, and metabolic disease have shown that gut permeability can be improved by a variety of agents including steroid hormones such as estrogen and progesterone, peptide hormones such as IGF-1, and SCFA such as butyrate." (PMID 33451354, 2021). "Moreover, we examined whether ghrelin affects the course of colitis directly or whether the effects of ghrelin are mediated by its influence on growth hormone and IGF-1 secretion." (PMID 28538694, 2017). "The process was found to increase IGF-1 levels and body weight in mice, but without affecting colitis." (PMID 39594627, 2024). "Animal experiments indicated that IGF-1 might be the key factor promoting the regeneration and repair of colonic mucosa in DSS-induced colitis." (PMID 33204338, 2020). "In our study, we found that thalidomide treatment in modeling or after modeling could reduce the overexpression of Th cell (Th1 and Th17) cytokines including IFN-γ, IGF-1, IL-6, IL-17 and TNF-α in serum and intestinal tissues in TNBS-induced colitis model." (PMID 31920668, 2019). "We observed lower IL‐4 expression in p38α‐ΔMC mice compared to WT mice, both during DSS‐induced colitis and in the tumors, and given that IL‐4 is a major IGF‐1 inducer, it could further contribute to the decreased levels of IGF‐1 signaling in p38α‐ΔMC mice." (PMID 29907597, 2018). "In order to optimize and maximize the therapeutic benefits of MSCs, we investigated whether cotransplantation of a chitosan (CS)-based injectable hydrogel with immobilized IGF-1 C domain peptide (CS-IGF-1C) and human placenta-derived MSCs (hP-MSCs) could ameliorate colitis in mice." (PMID 32685014, 2020). "Moreover, in hypophysectomized rats, administration of ghrelin failed to affect serum levels of GH or IGF-1, as well as the healing rate of colitis, mucosal cell proliferation, and mucosal concentration of IL-1β, or activity of myeloperoxidase." (PMID 28538694, 2017). "Serum concentration of IGF-1 in control pituitary-intact animals without colitis was 415.3 ng/mL." (PMID 28538694, 2017). "They found that increased levels of endogenous growth hormone and IGF-1 do not alter the susceptibility to DSS-induced colitis but enhance survival, reduce local inflammation, and accelerate mucosal repair in this model of experimental colitis." (PMID 28538694, 2017).